IL33 (interleukin 33)
Diseases named in the same sentence as IL33 in open-access papers (continued):
Sharing a sentence is not in itself a finding about the gene and the disease.
respiratory syncytial virus infection (1 paper, 2018). "Using murine alveolar epithelial cells or macrophage cells, the involvement of the MAPK signal pathway has been demonstrated in the IL-6 group of cytokines, oncostatin M- or respiratory syncytial virus infection-augmented IL-33 expression and production." (PMID 29587772, 2018).
retinal diseases (1 paper, 2023). "IL-33 plays an important regulatory role in glial-mediated retinal diseases, and bolstering the endogenous protective responses of IL-33 in Müller cells may be a novel approach to manage early-stage DR." (PMID 37671525, 2023).
rhegmatogenous retinal detachment (1 paper, 2024). Retinal detachment secondary to retinal tear or break. "The Ricker LJ study showed no significant changes in IL-33 in patients with recurrent PVR after rhegmatogenous retinal detachment (RRD) compared to those without postoperative PVR." (PMID 38455059, 2024).
rheumatic heart disease (1 paper, 2020). An autoinflammatory condition following an infection with Group A Beta Hemolytic Streptococcus (GABHS), in which the heart is attacked by antibodies formed in reaction to a recent GABHS infection. "This review elaborated on the role of ACE-I in reducing cardiac fibrosis in rheumatic heart disease progression through the inhibition of IL-33/sST2, providing a possible target for therapy against RHD." (PMID 32850979, 2020).
rosacea (1 paper, 2025). A chronic erythematous skin disorder that affects the face. "Gene expression quantification revealed an upregulation of inflammatory cytokines IL-33, IL-13, MCP-1, and IL-1ß that have been identified in the pathogenesis of rosacea." (PMID 41296102, 2025). "Furthermore, gene expression analysis revealed elevated levels of inflammatory cytokines IL-13, IL-33, MCP-1, IL-1β, and TNF-α in LL-37-treated mice, consistent with rosacea’s symptoms and serum MCP-1 level." (PMID 41296102, 2025).
Sciatica (1 paper, 2024). Pain in the lower back and hip radiating in the distribution of the sciatic nerve. "Conversely, there is a negative correlation between sciatica and Interleukin-1-alpha levels (p = 0.029, OR = 1.67E−05, 95% CI =8.79E−10–0.318), Interleukin-20 levels (p = 0.007, OR = 1.59E−06, 95% CI =8.95E−11–0.028), and Interleukin-33 levels (p = 0.029, OR = 7.62E−06, 95% CI =1.86E−10–0.312)." (PMID 39015317, 2024).
septic shock (1 paper, 2015). Shock caused by infection; frequently caused by gram negative bacteria, although some cases have been caused by other bacteria, viruses, fungi, and protozoa; characterized by fever, chills, tachycardia, tachypnea, and hypotension. "Different immune responses were observed between ST2-/- mice and IL-33-/- mice in allergic airway inflammation induced by “intraperitoneal” immunization of OVA, collagen-induced arthritis and LPS-induced septic shock." (PMID 26230091, 2015).
Shock (1 paper, 2015). The state in which profound and widespread reduction of effective tissue perfusion leads first to reversible, and then if prolonged, to irreversible cellular injury. "However, in certain mouse models for diseases such as allergic airway inflammation induced by intraperitoneal immunization with OVA, collagen-induced arthritis and LPS-induced septic shock, distinctly different immune responses were observed between ST2-/- mice and IL-33-/- mice." (PMID 26230091, 2015).
sickle cell disease (1 paper, 2022). Sickle cell anemias are chronic hemolytic diseases that may induce three types of acute accidents: severe anemia, severe bacterial infections, and ischemic vasoocclusive accidents (VOA) caused by sickle-shaped red blood cells obstructing small blood vessels and capillaries. "Plasma interleukin-33 levels, which were examined using ELISA, were demonstrated to be 2.05 ± 4.57 pg/mL and 1.50 ± 2.89 pg/mL in patients with sickle cell disease with ONFH and without ONFH, respectively." (PMID 35371856, 2022). "Our study found that plasma interleukin-33 levels were comparable in patients with sickle cell disease with or without ONFH." (PMID 35371856, 2022). "So, it was not clear whether plasma interleukin-33 levels were relevant in patients with sickle cell disease or not." (PMID 35371856, 2022). "Earlier studies have described the generally considered direct effects of IL-33 on the osteoclasts and its rising level in the circulation after its release from the necrotic cells, but the effect of IL-33 in patients with sickle cell disease with ONFH has not been described." (PMID 35371856, 2022).
Sm (1 paper, 2019). "Furthermore, a recent study showed that IL-33 needs to synergize with two other cytokine alarmins, thymic stromal lymphopoietin (TSLP) and IL-25, to induce IL-4/IL-13-dependent inflammation and fibrosis after Sm infection." (PMID 31200771, 2019).
small-bowel cancers (1 paper, 2020). "Specifically, in small-bowel cancers, MCs can act as major drivers of inflammation through IL-33/ST2-mediated signaling, promoting chronic inflammation and strongly skewing toward a Th17 immune response." (PMID 32098318, 2020). "The presence of IL-10 in conjunction with MC chemokines and alarmins such as IL-33 explains the pro-cancer, pro-inflammatory role MCs can play in certain cancers; in the context of small bowel cancers, MC protease expression resembled MMCs but included CTMC-related mast cell proteases too." (PMID 32098318, 2020).
squamous cell tumors of the (1 paper, 2025). "The study by Douglas Hanahan and colleagues found that squamous cell tumors of the cervix and skin, driven by Human Papillomavirus type 16 (HPV16), release four immunomodulatory factors ‒ IL-1α, IL-1β, IL-33, and IL-36β ‒ into the bloodstream." (PMID 41418390, 2025).
Strongyloides infection (1 paper, 2020). "To analyse the contribution of additional innate effector cells in mediating the rapid IL-33-driven S. ratti expulsion from the intestine we focused on basophilic, eosinophilic, and neutrophilic granulocytes that contribute to the control of Strongyloides infection alongside mast cells." (PMID 33351862, 2020).
T-cell lymphoma (1 paper, 2023). "However, unlike recombinant IL-33, recombinant GM-CSF did not inhibit tumor growth in the EG7 T-cell lymphoma model and TC-1 tumor model in TB mice; instead, it promoted tumor growth in the B16F10 tumor model." (PMID 37246159, 2023).
tauopathy (1 paper, 2021). Neurodegenerative disorders involving deposition of abnormal tau protein isoforms (tau proteins) in neurons and glial cells in the brain. "As defective glymphatic drainage has been linked to amyloid plaque and tauopathy, we asked if IL33 was also involved in the regulation of glymphatic drainage." (PMID 33432186, 2021). "Defects in those mechanisms together may lead to chronic neurodegeneration and tauopathy at old age in IL33-deficient mice." (PMID 33432186, 2021).
tonsillitis (1 paper, 2021). Inflammation of the tonsillar tissue. "Although salivary levels of IL-6, IL-33 and TNF-α were significantly increased in patients with recurrent tonsillitis compared to healthy controls, these parameters were unable to differentiate between the diagnosis groups since significance was only achieved through single outliers." (PMID 34187480, 2021).
type 1 AIP (1 paper, 2020). "Diagnostic performance of serum IFN-α and IL-33 concentrations as markers of type 1 AIP and/or IgG4-RD was comparable to that of serum IgG4 concentration, as calculated by the receiver operating characteristic curve analysis." (PMID 32938972, 2020). "We next evaluated the utility of serum IFN-α and IL-33 concentrations as diagnostic biomarkers for type 1 AIP/IgG4-RD." (PMID 32938972, 2020). "These parameters obtained by ROC curve analysis showed that the serum levels of IFN-α and IL-33 may be useful as diagnostic biomarkers for type 1 AIP/IgG4-RD (in addition to the well-established serum concentration of IgG4)." (PMID 32938972, 2020). "Our previous studies provided evidence that pancreatic accumulation of pDCs, which may produce large amounts of IFN-α and IL-33, underlies the immunopathogenesis of type 1 AIP and IgG4-RD1,15–19." (PMID 32938972, 2020). "Therefore, it is likely that systemic as well as in situ production of IFN-α and IL-33 might underlie the immunopathogenesis of type 1 AIP and IgG4-RD." (PMID 32938972, 2020). "In line with the positive correlation observed between the serum IFN-α and total IgG, IgG1, or IgG4 levels, we found significant positive correlations between IL-33 and total IgG or IgG4 concentrations in the serum of patients with type 1 AIP/IgG4-RD." (PMID 32938972, 2020). "Here, we provide evidence that measurements of serum IFN-α and IL-33 concentration are useful for the diagnosis and evaluation of disease activity in patients with type 1 AIP/IgG4-RD." (PMID 32938972, 2020). "In this study, we assessed the utility of serum IFN-α and IL-33 levels as biomarkers for type 1 AIP and IgG4-RD." (PMID 32938972, 2020). "Recently, we reported that the development of experimental AIP and human type 1 AIP is associated with increased expression of IFN-α and IL-33 in the pancreas." (PMID 32938972, 2020). "We conclude that serum IFN-α and IL-33 concentrations can be useful as biomarkers for type 1 AIP and IgG4-RD." (PMID 32938972, 2020). "Taken together, these data strongly suggest that serum concentrations of IFN-α and IL-33 can be useful biomarkers not only for the diagnosis of type 1 AIP/IgG4-RD, but also for the assessment of disease activity." (PMID 32938972, 2020). "In contrast, markedly higher concentrations of IFN-α and IL-33 were seen in patients with type 1 AIP/IgG4-RD as compared to those in CP patients." (PMID 32938972, 2020). "Positive correlations between IgG4, IFN-α, and IL-33 levels were seen in type 1 AIP/IgG4-RD patients." (PMID 32938972, 2020). "Although the data presented in this study support the utility of serum IFN-α and IL-33 as biomarkers of type 1 AIP/IgG4-RD, our study had several limitations." (PMID 32938972, 2020). "A strong positive correlation between the serum concentrations of IFN-α and IL-33 was seen in patients with type 1 AIP/IgG4-RD." (PMID 32938972, 2020). "Based on our previous data, in the present study, we tested the hypothesis that serum concentrations of IFN-α and IL-33 could be useful biomarkers for type 1 AIP and IgG4-RD." (PMID 32938972, 2020). "Therefore, we conclude that the serum concentrations of IFN-α and IL-33 may serve as biomarkers for the diagnosis of type 1 AIP/IgG4-RD, as well as for monitoring purposes." (PMID 32938972, 2020). "In conclusion, we found that the serum of patients with type 1 AIP/IgG4-RD showed high concentrations of IFN-α and IL-33, which, in turn, positively correlated with the serum IgG4 levels." (PMID 32938972, 2020). "We found that patients with type 1 AIP/IgG4-RD exhibited higher serum concentrations of IgG4, IFN-α, and IL-33, compared with those in patients with CP or HCs." (PMID 32938972, 2020). "In this study, we found that type 1 AIP/IgG4-RD patients exhibited higher serum concentrations of IFN-α and IL-33 than patients with CP or HCs." (PMID 32938972, 2020).
type 1 AIP (continued). "As has been shown in previous reports, including our own, the activation of IFN-α and IL-33 is involved in the immunopathogenesis of experimental AIP and human type 1 AIP/IgG4-RD1,15–19,30,31." (PMID 32938972, 2020). "In contrast, elevated serum concentrations of IL-33 seen in type 1 AIP/IgG4-RD have not been reported in SLE33." (PMID 32938972, 2020). "Thus, these serum cytokine assays revealed that patients with type 1 AIP and IgG4-RD were characterized by elevated serum IFN-α and IL-33 concentrations." (PMID 32938972, 2020). "Collectively, these data suggest that the serum of type 1 AIP/IgG4-RD patients contains higher concentrations of total IgG, IgG1, IgG4, IFN-α, and IL-33, and that the activation of IFN-α and IL-33-mediated signaling pathways is involved in IgG4-biased Ig class switch recombination." (PMID 32938972, 2020). "Thus, patients with type 1 AIP/IgG4-RD are characterized by enhanced IFN-α and IL-33 responses not only in the pancreas but also in the serum." (PMID 32938972, 2020). "However, the utility of serum IFN-α and IL-33 levels as biomarkers of type 1 AIP/IgG4-RD has never been evaluated." (PMID 32938972, 2020). "Furthermore, we had a case of type 1 AIP and IgG4-RD in which the serum concentrations of IFN-α and IL-33, rather than the serum concentration of IgG4, were highly associated with disease activity." (PMID 32938972, 2020). "Therefore, the activation of signaling pathways triggered by IL-33 and IFN-α may be involved in the clinical manifestations specific to type 1 AIP and IgG4-RD, but not to SLE." (PMID 32938972, 2020).
type-2 diabetic nephropathy (1 paper, 2019). "Short Description: A novel bifunctional cytokine IL233, bearing IL-2 and IL-33 activities reverses inflammation and protects from type-2 diabetic nephropathy through promoting T-regulatory cells and type 2 immune response." (PMID 31191312, 2019).
urinary obstruction (1 paper, 2022). "In the unilateral urinary obstruction mouse model, IL-33 or ST2 deficiency reduced kidney injury and fibrosis, while in a mouse model of ischaemia reperfusion injury (IRI), blocking IL-33 with sST2 resulted in reduced pro-fibrotic myofibroblast accumulation." (PMID 38566909, 2022).
viral fulminant hepatitis (1 paper, 2013). "The liver sinusoidal endothelial cells, vascular endothelial cells and hepatocytes are potential sources of IL-33 during viral fulminant hepatitis and NK cells partially regulate hepatocyte-specific IL-33 expression." (PMID 24058536, 2013). "The cellular sources of IL-33 in viral fulminant hepatitis are not well known." (PMID 24058536, 2013). "Despite the fact that IL-33 is proposed to be released as an alarmin in acute inflammatory pathologies, the expression and cellular sources of IL-33 during viral fulminant hepatitis in a relevant animal model has not been explored." (PMID 24058536, 2013).
viral respiratory tract infection (1 paper, 2016). A respiratory tract infection caused by a virus. "TSLP has not previously been recognized to affect ILC2s during viral respiratory tract infection; however, it is a known stimulus of ILC2s in other disease models and can be released from epithelial cells in a fashion to IL-33 and IL-25." (PMID 27156176, 2016).
tumor (593 papers, 2008 to 2026). "The release of these secretory products through degranulation causes tumor cell death and this process can be enhanced by several soluble mediators, including IL-5, IL-33, CCL11 and IFN-γ." (PMID 40050933, 2025). "In oestrogen receptor-positive breast cancer, elevated levels of IL-33 and sST2 are associated with tumour aggressiveness and resistance to treatment." (PMID 41284319, 2025). "Elevated IL-33 expression is associated with reduced efficacy of chemotherapeutic drugs in tumor cells, as nuclear IL-33 is also implicated in the repair of DNA double-strand breaks." (PMID 40216748, 2025). "In this study, we found that both cancer-associated fibroblasts (CAFs) and tumor cells treated with DNA damage-inducing agents expressed and secreted high levels of IL-33, subsequently leading to enhanced DNA damage repair efficacy." (PMID 40216748, 2025). "While TNF-α is a proinflammatory cytokine, crucial for promoting a strong and functional type 1 anti-tumor immune response, IL-33 and IL-4 are associated with immunosuppression and tumor promotion." (PMID 40943444, 2025). "Higher levels of serum IL13 were associated with high tumor grade (P = 0.031), and higher serum IL33 levels were associated with younger age (P = 0.013)." (PMID 40928327, 2025). "In GCs, elevated IL-33 and IL-13 levels have been linked to enhanced tumor-associated macrophage activation, which promotes immune evasion." (PMID 40761291, 2025). "IL-33-driven type 2 immunity is generally associated with tumor promotion in both preclinical studies and human prognostic and genetic association studies." (PMID 41087719, 2025). "The increase and promotion of MDSCs are linked to tumor development and heightened immunosuppression due to IL-33." (PMID 40236667, 2024). "The role of eosinophils is functionally linked to the presence of IL-33 in the microenvironment and has been controversial regarding anti-tumor immunity, which largely depends on the tumor type and the immune cell populations within the microenvironments." (PMID 38524132, 2024). "Through the utilization of IL-33−/− mice, we demonstrate that the loss of host-derived IL-33 promotes tumor growth and induces alterations in the infiltration patterns of ILC2s, CD4+ T cells, and CD8+ T cells." (PMID 38430390, 2024). "IL-33-deficient Tregs exhibit compromised suppressive capabilities and aid in the elimination of tumors as well as the development of strong anti-tumor immunity." (PMID 39227959, 2024). "IL-33 combined with anti-CSF1R or p38 inhibitor to regulate tumor-associated macrophages (TAMs) had a synergistic antitumor effect." (PMID 38238529, 2024). "In summary, the data proved that the local inflammatory milieu mediated by IL-33 induced the recruitment of tumor-associated peritoneal macrophages and activation of tumor immune environment." (PMID 38238529, 2024). "The protumoral effect of IL-33 is not limited to immune cells, as IL-33 can directly induce the proliferation or migration of tumor-associated cells." (PMID 38825642, 2024). "Understanding the mechanisms underlying IL-33’s dual role as both a promoter and inhibitor of tumor progression is essential for refining therapeutic strategies and fully realizing its potential in cancer immunotherapy." (PMID 38881897, 2024). "Recent findings from our research highlight the direct association between the tumor-suppressive effects of exogenous IL-33 and a novel subset of highly immunogenic cDC1s." (PMID 38825642, 2024). "Recently, it was shown that IL-33 is associated with a poor prognosis in several cancer types, even though in certain circumstances it acts as a tumor suppressor by triggering an immune response." (PMID 39839625, 2024). "Bag6-deficiency allowed the release of EV-associated IL33 which modulate the TME via MC activation promoting aggressive tumor growth." (PMID 38942797, 2024).